ATM (ATM serine/threonine kinase)
Diseases named in the same sentence as ATM in open-access papers (continued):
Sharing a sentence is not in itself a finding about the gene and the disease.
diabetes (continued). "ATM-EVs contain high levels of miR-210, and miR-210 in ATM-EVs has been shown to regulate glucose uptake and mitochondrial chain complex IV activity by targeting NDUFA4 gene expression, which promotes the pathogenesis of diabetes." (PMID 34975877, 2021). "It is also important to note that of the six patients with glucose metabolism disorders and one with diabetes, five of them had compromised lean mass and six had high NHDL-c values, which reinforces risk factors for developing CV disease dependent on ATM activity (data not shown)." (PMID 28778179, 2017).
hepatocellular carcinoma (28 papers, 2011 to 2026). A malignant tumor that arises from hepatocytes. "As heterozygous carriers of ATM variants may have an increased risk of cancer, this variant could be an additional genetic cause for the development of the patient's hepatocellular carcinoma." (PMID 39180521, 2024). "Caffeine pretreatment could significantly abate the G2-M arrest caused by Q6 in hepatocellular carcinoma, which suggested Q6 induced G2-M arrest was caused by DNA DSBs which were sensed by ATM pathway." (PMID 26649750, 2015). "Flavonoid-induced apoptosis in cancer cells via elevation of intracellular ROS levels has been shown in several reports, although previous reports have also shown that butein induces ROS generation, modulates JNK, ATM, and Chk activity, and causes G2/M arrest in hepatoma cells." (PMID 22245810, 2012). "It has been suggested that ATM expression is lower in hepatocellular carcinoma and leads to poor patient outcomes." (PMID 37059591, 2023). "CDK5 was shown to phosphorylate ataxia telangiectasia mutated (ATM) protein at Ser729, thereby activating the DDR pathway in hepatocellular carcinoma cell lines." (PMID 31910742, 2020). "As has been shown in 2011, inhibition of ATM in rat hepatoma cell lines diminished the effect of metformin by reduced phosphorylation and activation of AMP-activated protein kinase." (PMID 32733823, 2020). "To confirm the effect of RMP on the expressions of p-ATM, p-p65 and Bcl-xl, we further examined the expression levels of these proteins in tumor tissues from nude mice with hepatoma." (PMID 31754340, 2019). "Indeed, Ehrlich and colleagues reported that CDK5 activity blockade in hepatocellular carcinoma cell lines prevented ATM phosphorylation and then blocked the initiation of the DNA damage response, including the G2/M arrest." (PMID 32708903, 2020). "Based on RT-qPCR analysis of Orox A-treated hepatocellular carcinoma cells, significant increases in the mRNA transcript levels of NEIL1, OGG1, ATR, and ATM were observed." (PMID 41009509, 2025). "Using a model of chemically induced hepatocellular carcinoma in mouse liver, we comparatively analyzed the dynamics of transcript levels for several genes (BRCA1, BRCA2, CHEK1, CHEK2, ATM, CDK12) in paired samples of normal and tumor tissue over a 24-h PMI using RT-qPCR." (PMID 42073491, 2026).
Nijmegen breakage syndrome (28 papers, 2008 to 2025). Nijmegen breakage syndrome is a rare genetic disease presenting at birth with microcephaly, dysmorphic facial features, becoming more noticeable with age, growth delay, and later-onset complications such as malignancies and infections. "Varying degrees of antibody deficiency have also been noted in chromosomal instability syndromes such as ataxia-telangiectasia (A-T, ATM mutations), Nijmegen breakage syndrome (NBS, NBS1 mutations), and ataxia-telangiectasia-like disorder (ATLD, MRE11 mutations)." (PMID 20805886, 2010). "The central role of the DDR in human physiology is indicated by a broad spectrum of disorders described in individuals carrying mutations in DDR genes, such as ataxia telangiectasia mutated (ATM) and Nijmegen breakage syndrome (NBS)." (PMID 28471392, 2017). "The colony formation assay demonstrates that cells with homozygous mutations in the Nijmegen Breakage Syndrome (NBS) and Ataxia-Telangiectasia Mutated (ATM) genes are extremely sensitive to IR." (PMID 41210219, 2025). "As such, cells derived from ataxia-telangiectasia-like disease (ATLD) and Nijmegen breakage syndrome (NBS) patients that express mutant forms of either MRE11 or NBS1, respectively, display greatly reduced ATM activation and a predisposition to cancer development." (PMID 27568553, 2016). "Mutations in ATM (Ataxia Telangiectasia Mutated), MRE11, NBS1 (Nijmegen Breakage Syndrome), BRCA1 (Breast Cancer 1), BRCA2 and Ligase 4 cause human syndromes characterized by both CABs and cancer predisposition, highlighting the connection between CABs and cancer." (PMID 24651653, 2014). "Mutations in ATM, Mre11 and NBS1 are found in patients with Ataxia Telangiectasia (A-T), Ataxia Telangiectasia-like disorder (A-TLD) and Nijmegen breakage syndrome (NBS), respectively." (PMID 29254281, 2017). "Clearly the MRN complex plays a very important role in ATM function, particularly considering the similarity in clinical phenotypes of patients lacking ATM (A-T) compared with patients expressing hypomorphic alleles of MRE11 or RAD50 (A-T-like Disorder) or Nbs1 (Nijmegen Breakage Syndrome)." (PMID 23525106, 2013). "Nijmegen breakage syndrome (NBS), which is caused by a hypomorphic mutation in the NBS1 gene, and ataxia telangiectasia (A-T), which is caused by mutations in the ATM gene, highlight the significance of NBS1 in DSB repair." (PMID 18211700, 2008). "For instance, Mre11, Nbs1, ATM and BRCA1, which play critical roles in DNA damage checkpoint and DSB repair are linked ataxia-telangiectasia-like disorder (ATLD), Nijmegen breakage syndrome (NBS), ataxia-telangiectasia and familial breast cancer, respectively." (PMID 23468639, 2013).
osteosarcoma (27 papers, 2011 to 2025). A usually aggressive malignant bone-forming mesenchymal neoplasm, predominantly affecting adolescents and young adults. "We have previously shown that MSeA treatment (LD50, 4 μmol/L) kills HCT116 colorectal, PC-3 prostate and U-2 OS osteosarcoma cells in association with reactive oxygen species (ROS), ATM and DNA-PKcs." (PMID 25010594, 2014). "Furthermore, Aven is required for ataxia telangiectasia-mutated (ATM) activation in Xenopus oocytes and HeLa cells and ataxia telangiectasia-related activation following DNA damage in osteosarcoma cells." (PMID 26267306, 2015). "Collectively, our results identify A1BG as a critical adipocyte‐derived protein that mediates cisplatin resistance in osteosarcoma by promoting PARP1/ATM‐dependent DNA repair." (PMID 40560034, 2025). "To identify the mechanism involving in Licochalcone A-induced G2/M phase arrest in osteosarcoma cells, we tested the activation of ATM-Chk2 and ATR-Chk1, the primary pathway for activating G2/M checkpoint." (PMID 31269698, 2019). "We validated the chicken Atm–Rsf1 complex by co-immunoprecipitation of human RSF1 with human ATM using U2OS osteosarcoma cells." (PMID 24800743, 2014). "To test this, we assessed the expression of A1BG and DNA repair‐related proteins (PARP1, ATM, and p‐ATM) at various time points (0, 6, 12, and 24 h) following cisplatin treatment in osteosarcoma cells under A1BG‐depleted or recombinant A1BG‐supplemented conditions." (PMID 40560034, 2025). "Among them, MLLT3, ATM/ATR, DDX10, CASP1 and BRD4 have been extensively studied and shown to be associated with pathogenesis or clinical outcomes in osteosarcoma." (PMID 37894336, 2023). "In addition, we performed flow cytometry analysis for apoptosis after co-treatment of doxorubicin and an ATM inhibitor/PARP inhibitor in osteosarcoma cells in which the overexpression of SIRT6 had been induced." (PMID 33198792, 2020). "Therefore, we evaluated the effect of co-treatment of doxorubicin and an ATM inhibitor/PARP inhibitor in osteosarcoma cells in which the overexpression of SIRT6 had been induced." (PMID 33198792, 2020). "Our data further indicated that the activation of ATM/Chk2 and autophagy may be involved in Licochalcone A-induced anti-proliferating effect in osteosarcoma cell lines." (PMID 31269698, 2019). "Furthermore, we found the Licochalcone A exposure resulted in rapid ATM and Chk2 activation, and high levels of nuclear foci of phosphorylated Chk2 at Thr 68 site in osteosarcoma cell lines." (PMID 31269698, 2019). "We evaluated the prognostic significance of SIRT6 in 37 osteosarcomas and investigated the therapeutic efficacy of SIRT6 on the anticancer effects of doxorubicin, olaparib, and ATM inhibitor." (PMID 33198792, 2020).
osteosarcoma (continued). "However, Aqeilan and al. found that WWOX activates HR in the osteosarcoma cells U2OS, by interacting with ATM and stimulating its kinase activity." (PMID 37248434, 2023). "The signaling pathways involved in tumor progression of Osteosarcoma are the FOXM1 transcription pathway, ATM signaling pathway, FAK mediated signaling events, Arf6 signaling events, Class 1 PI3K signaling events, mTOR signaling pathway, and Integrin family cell surface interactions." (PMID 37081847, 2023).
Insulin resistance (26 papers, 2012 to 2025). Increased resistance towards insulin, that is, diminished effectiveness of insulin in reducing blood glucose levels. "Taken together, adipose tissue‐derived cytokines causing insulin resistance were proven to be significantly diminished in mouse models via phenotype switching of ATM by PBP‐NPs containing HO‐1 inducers." (PMID 36209391, 2022). "Further, animal studies demonstrated that loss of one or both alleles of ATM increases the symptoms of metabolic syndrome, including glucose intolerance and insulin resistance in ApoE−/− mice fed on a high-fat diet." (PMID 35453338, 2022). "They showed that during insulin resistance induced by ATM deficiency, JNK was activated, which consequently increased the level of inhibitory serine-307 phosphorylation on the insulin receptor substrate-1 (IRS-1) and caused insulin resistance." (PMID 35453338, 2022). "High fat diets and ATM deficiency independently associate with the development of insulin resistance." (PMID 36117462, 2022). "Animal studies have also shown that mutation in one or two ATM alleles worsen the features of metabolic syndrome, increase insulin resistance, and accelerate atherosclerosis in apoE−/− mice." (PMID 28806901, 2017). "ATM deficiency is associated with insulin resistance and diabetes." (PMID 35453338, 2022). "Deficiencies in ATM have been linked to insulin resistance and type 2 diabetes." (PMID 28754146, 2017). "It has been shown that ATM‐deficient mice exhibit glucose intolerance, insulin resistance and impaired insulin secretion 5, 6, while interactions of this protein kinase with multiple components of insulin signalling (JNK, PI3K, IRS2 and AKT) have been observed in in vitro studies." (PMID 26606753, 2016). "In addition, skeletal muscles of rats with induced insulin resistance via high fat diet feeding displayed lowered ATM protein levels suggesting a role of ATM deficiency in the development of T2DM." (PMID 23776597, 2013). "A study of mice with a heterozygous ATM mutation and apolipoprotein E deficiency, involved in the redistribution of triglycerides and cholesterol in different tissues, showed accelerated progression of atherosclerotic lesions in association with insulin resistance and glucose intolerance." (PMID 40597142, 2025). "Studies conducted in mouse models with ATM mutations have demonstrated a high susceptibility to insulin resistance and hypercholesterolemia, which are the two cardiovascular risk factors that could potentially account for the increased predisposition to atherosclerosis." (PMID 39326070, 2024). "These genes have been involved in insulin resistance and secretion (ATM, PTPRN2, PSMD10, and NSF), adipogenesis (SLC25A24 and PAX8), inflammatory processes (TNFRSF8 and SLIT3), and mitochondrial processes (PM20D1 and LCLAT1)." (PMID 36535927, 2022). "In skeletal muscle, RSV ameliorates high-fat diet-induced insulin resistance and fatty acid oxidation via the ATM-AMPK axis." (PMID 35431994, 2022). "Interestingly, some of the pathological phenotypes identified in A-T, including insulin resistance, premature aging, and neurodegeneration cannot be easily connected to the well-known role of ATM in DDR, while conversely, they could be linked to the interplay between ATM and ROS." (PMID 29616191, 2018). "ATM haploinsufficiency results in atherosclerotic lesions in apoE null mice accompanied by insulin resistance and glucose intolerance." (PMID 29152614, 2017). "ATM is involved in insulin resistance, TGF-beta, and FOXO1 pathways in the constructed interactome." (PMID 39457593, 2024). "Furthermore, insulin resistance was decreased when ATM-EXOs from lean mice, which had lower miR-155 levels, were injected into obese mice." (PMID 37372020, 2023). "Notably, adipose tissue macrophage-derived exosomes, termed ATM-EXOs, isolated from obese mice have been shown to confer insulin resistance and glucose intolerance when injected into lean mice." (PMID 37372020, 2023).
Insulin resistance (continued). "Besides, improvement in insulin resistance was observed when ATM-EXOs from lean mice were injected into obese mice." (PMID 37372020, 2023). "Therefore, the reduced PI3K/Akt signaling during ATM deficiency appears to contribute to the decrease in GLUT4 translocation and insulin resistance." (PMID 35453338, 2022). "The observed increase in fasting blood glucose levels in ATM‐deficient female, not male, mice point toward the possibility of sex‐specific differences in insulin resistance with WD." (PMID 36117462, 2022). "Other results suggest that lower ATM levels in a rat model fed a high-fat diet may contribute to the development of insulin resistance by downregulating Akt activity, since defective Akt activation is an important mechanism in the development of this resistance." (PMID 35453338, 2022). "ATM activation by the anti-malarial drug chloroquine decreases macrophage JNK activation, blood pressure, insulin resistance, and atherosclerosis in mice." (PMID 31384309, 2019). "The absence of ATM in mice affects hepatic insulin sensitivity and promotes atherosclerosis, suggesting the involvement of processes that link hepatic insulin resistance and vascular disease." (PMID 31384309, 2019). "A-T patients lacking functional ATM display features of premature aging, accompanied by insulin resistance and glucose intolerance." (PMID 29717979, 2018).